UNC45A (unc-45 myosin chaperone A)
Description:
Acts as a co-chaperone for HSP90. Prevents the stimulation of HSP90AB1 ATPase activity by AHSA1. Positive factor in promoting PGR function in the cell. May be necessary for proper folding of myosin (Potential). Necessary for normal cell proliferation. Necessary for normal myotube formation and myosin accumulation during muscle cell development. May play a role in erythropoiesis in stroma cells in the spleen (By similarity).
Synonyms: Unc-45A; SMAP-1; SMAP1; GC-UNC45; GCUNC-45; GCUNC45; IRO039700; OOHE
Tractability: PROTAC: ubiquitination databases record sites on it; its protein half-life has been measured.
Gene: Protein-coding gene on chromosome 15 (90,930,180 to 90,954,093, forward strand). Ensembl gene ENSG00000140553.
Subcellular location: Cytoplasm; Cytoplasm, perinuclear region; Nucleus
Subcellular location (Human Protein Atlas): Nuclear speckles; Cytosol
Gene Ontology:
Molecular function: cadherin binding; identical protein binding; protein binding; Hsp90 protein binding
Biological process: protein folding
Cellular component: cytosol; nuclear speck; cytoplasm; nucleus; perinuclear region of cytoplasm
Genetic constraint (gnomAD): Loss-of-function variants: 78 observed, 106.46 expected, observed/expected ratio (o/e) 0.73, 90% interval 0.61 to 0.88. The upper end of that interval is the gene's LOEUF score, 0.88, which puts it in group 3 of 6, group 1 being the genes least tolerant of losing a copy. Missense variants: 1,193 observed, 1,266.2 expected, observed/expected ratio (o/e) 0.94, 90% interval 0.9 to 0.99. Synonymous variants: 495 observed, 527.08 expected, observed/expected ratio (o/e) 0.94, 90% interval 0.87 to 1.01.
Homologues: Orthologues: chimpanzee UNC45A (99% identical), macaque UNC45A (99% identical), mouse Unc45a (94% identical), guinea pig UNC45A (94% identical), dog UNC45A (93% identical), rat Unc45a (93% identical), pig UNC45A (92% identical), tropical clawed frog unc45a (70% identical), zebrafish unc45a (64% identical), Drosophila melanogaster unc-45 (35% identical), Caenorhabditis elegans unc-45 (33% identical). Paralogues in human: UNC45B (56% identical), SPAG1 (11% identical), RPAP3 (10% identical), TTC12 (9% identical), STIP1 (9% identical), TOMM34 (9% identical), TOMM70 (8% identical), SPATA16 (7% identical), ST13 (7% identical), DNAAF4 (7% identical), TTC4 (6% identical), STUB1 (6% identical), and 6 more.
Diseases named in the same sentence as UNC45A in open-access papers:
UNC45A is named in the same sentence as 21 diseases in open-access papers, as found by Europe PMC text mining. Sharing a sentence is not in itself a finding about the gene and the disease. The quoted sentences say what the papers report.
deafness (6 papers, 2021 to 2025). An inherited or acquired condition characterized by the complete loss of the ability to hear from one or both ears. "Variants in the UNC45A cochaperone have been recently associated with a syndrome combining diarrhea, cholestasis, deafness, and bone fragility." (PMID 35575086, 2022). "Intriguingly, loss-of-function mutations in UNC45A are associated with a human form of syndromic deafness, although it is unknown whether this is caused by defective hair cell stereocilia formation, similar to the phenotype caused by pathogenic Myo15 variants in mouse." (PMID 33372036, 2021). "Loss-of-function mutations in the myosin cochaperone UNC45A lead to the onset of O2HE syndrome in newborns, characterized by manifestation of all or a number of these symptoms: severe diarrhea, cholestasis, deafness, bone fragility, and mild intellectual disability." (PMID 40125554, 2025).
cholestasis (5 papers, 2021 to 2025). Impairment of the bile flow caused by obstruction within the liver, or outside the liver in the bile duct system. "A syndrome that variably combines congenital diarrhea, cholestasis, loss of hearing, and bone fragility was recently described in 3 families and ascribed to loss-of-function (LoF) variants in UNC45A." (PMID 35575086, 2022). "The osteo-oto-hepato-enteric (O2HE) syndrome (OMIM #619377), which combines congenital secretory diarrhea, cholestasis, hearing impairment, and bone fragility, has recently been linked to loss-of-function mutations in the Unc-45 myosin chaperone A (UNC45A) gene, encoding a myosin cochaperone." (PMID 40125554, 2025). "Interestingly, congenital loss-of-function mutations in UNC-45A cause a syndrome characterized by diarrhea, cholestasis, bone fragility, and impaired hearing, all of which symptoms involve organs where cilia play important roles in physiology." (PMID 34206743, 2021). "Apart from the association of Unc-45 Myosin Chaperone A (UNC45A) with syndromal diarrhea and cholestasis, no other genes identified in our CRISPR screen have been published in this context to date." (PMID 36661306, 2023). "We do not know whether the UNC45A mutations reported in O2HE patients who did present with cholestasis will lead to a similar loss of myosin Vb expression and whether any myosin Vb remaining will function properly in the absence of UNC45A or may behave as a dysfunctional/mutant-like myosin Vb." (PMID 35421597, 2022).
ovarian carcinoma (4 papers, 2012 to 2021). A malignant neoplasm originating from the surface ovarian epithelium. "This is consistent with previous reports and, especially in ovarian cancer, UNC-45A is necessary to support the growth of cancer cells and to develop chemoresistance to paclitaxel." (PMID 34206743, 2021). "UNC-45A is overexpressed in breast and ovarian cancer as compared to their normal counterpart and in ovarian cancer patients that are resistant to the MT-stabilizing drug paclitaxel." (PMID 34206743, 2021). "In humans, there is a positive correlation between levels of Unc45a and the stage and grade of ovarian cancer." (PMID 23144999, 2012). "This can be attributed, in part, to the elevated levels of Unc45a protein in ovarian carcinoma tumours compared to healthy ovarian epithelium." (PMID 23144999, 2012). "Thus, we examined TNT formation in ovarian cancer cells with intact UNC-45A expression as compared with the same cell line (SKOV3) with shRNA knockdown of UNC-45A; a scramble version of the lentivirus offered an additional form of control." (PMID 30333973, 2018). "As regulators of actomyosin contractility and MT stability are essential for the physiopathology of the female reproductive tract and of neuronal development, our findings suggest that UNC-45A may have a role in ovarian cancer initiation and development as well as in neurodegeneration." (PMID 34206743, 2021).
breast carcinoma (3 papers, 2020 to 2023). "UNC-45A functions as a mitotic spindle-associated protein that destabilizes microtubule activity and was overexpressed in human ovarian and breast cancers, and its loss results in reduced cell proliferation." (PMID 37686380, 2023). "We and others have previously shown that UNC-45A is expressed in human ovarian surface epithelial cells and human breast cells and overexpressed in highly proliferative cells of ovarian and breast cancers as compared to their normal counterpart." (PMID 34206743, 2021). "A recent breast cancer-related study provides solid evidence that UNC45A nuclear localization promotes the expression of the mitotic kinase NEK7 and that the mitotic catastrophe resulting from UNC45A deficiency can be rescued by heterologous NEK7 expression." (PMID 33364979, 2020).
enteropathies (2 papers, 2022 to 2025). "We have previously shown that UNC45A mutations are responsible for microvillus inclusion disease–like (MVID-like) enteropathy with clinical symptoms of variable severity." (PMID 40125554, 2025). "The patterns of p.Leu237Pro variant and UNC45A-KO cells displayed the full range of ultrastructural abnormalities of MVID-like enteropathy similar to P1.1’s enterocytes." (PMID 40125554, 2025). "In this study we tested the hypothesis that UNC45A and myosin Vb, the losses of which are associated with 2 rare diseases with shared enteropathy, are functionally linked." (PMID 35421597, 2022). "Recently, we have shown that loss of UNC45A chaperone activity on the myosin motor protein VB (MYO5B) causes abnormal apicobasal vesicle trafficking in enterocytes and promotes enteropathies in the O2HE syndrome." (PMID 40125554, 2025).
Intellectual disability (2 papers, 2021 to 2025). "Furthermore, almost all of the subjects affected by congenital UNC-45A loss have signs of intellectual disability." (PMID 34206743, 2021).
atherosclerosis (1 paper, 2020). A disease characterized by the build-up of fatty material and calcium deposition in the arterial wall resulting in partial or complete occlusion of the arterial lumen. "Lastly, WIZ and UNC45A were found to be the two DEGs mostly associated with two atherosclerosis subtypes." (PMID 33381146, 2020).
cardiomyopathies (1 paper, 2024). "Four variants, c.302G>C/p.Gly101Ala (CAPN1), c.637C>T/p.Arg213Trp (MTUS2), c.457C>T/p.Arg153Cys (CRTAC1), c.1309G>T/p.Gly437Cys (UNC45A), were associated with cardiomyopathies." (PMID 38848015, 2024). "The variant in UNC45A was associated with cardiomyopathy (p=0.036) in FinnGen and the variant in UNC45B was associated with heart failure (p=0.049)." (PMID 38848015, 2024).
ciliopathies (1 paper, 2021). "Taken together, our results also suggest that UNC-45A may play a role in the physiology of ciliated epithelia as well as in ciliopathies." (PMID 34206743, 2021).
intrahepatic cholestasis (1 paper, 2022). A cholestasis characterized by impairment of the bile flow caused by obstruction located in the liver. "UNC45A is a myosin (co-)chaperone, and mutations in the UNC45A gene were recently identified in osteo-oto-hepato-enteric (O2HE) syndrome patients presenting with congenital diarrhea and intrahepatic cholestasis." (PMID 35421597, 2022). "Because UNC45A mutations have also been associated with intrahepatic cholestasis in some O2HE patients, we examined the effect of UNC45A depletion on myosin Vb expression in hepatocellular HepG2 cells, widely used model cell lines for the study of hepatocellular biology." (PMID 35421597, 2022). "Notably, the O2HE patient with the UNC45A-p.V423D mutation did not display intrahepatic cholestasis." (PMID 35421597, 2022).
melanoma (1 paper, 2020). A malignant, usually aggressive tumor composed of atypical, neoplastic melanocytes. "For each of the genes, namely ZNFx1, RHPN2, STK11IP and UNC45A, from 1 to 3 siRNAs were designed and tested in melanoma cell line A375." (PMID 33041669, 2020). "It is tempting to speculate that the maintenance of UNC45A is essential for masking of highly immunogenic melanoma cells from the restrictive actions of immune system." (PMID 33041669, 2020). "Here we present the results of transient siRNA-mediated knockdown of the four of such genes, namely, UNC45A, STK11IP, RHPN2 and ZNFX1, in melanoma cell line A375, then assayed the cells for their viability, proliferation and ability to migrate in vitro." (PMID 33041669, 2020).
microvillus inclusion disease (1 paper, 2022). Microvillus inclusion disease (MVID) is a very rare, severe, malabsorbative syndrome characterized clinically by protracted or intractable neonatal secretory diarrhea and histologically by inclusion bodies on the intestinal epithelium. "Taken together, our results provide evidence that UNC45A plays an essential role in epithelial morphogenesis through its cochaperone function of myosin VB and that UNC45A loss causes a variant of microvillus inclusion disease." (PMID 35575086, 2022).
osteosarcoma (1 paper, 2025). A usually aggressive malignant bone-forming mesenchymal neoplasm, predominantly affecting adolescents and young adults. "Absence of the myosin cochaperone leads to misfolding and aggregation of NMII and to abnormal shape and impaired maturation of focal adhesions of UNC45A-deficient human osteosarcoma (U2OS) cells." (PMID 40125554, 2025). "The UNC45A p.Leu237Pro mutant retained chaperone activity, prevented myosin aggregation, and supported proper nonmuscle myosin II (NMII) filament formation in patient fibroblasts and human osteosarcoma (U2OS) cells." (PMID 40125554, 2025).
X-linked adrenoleukodystrophy (1 paper, 2021). X-linked adrenoleukodystrophy (X-ALD) is a peroxisomal disorder resulting in cerebral demyelination, axonal dysfunction in the spinal cord leading to spastic paraplegia, adrenal insufficiency and in some cases testicular insufficiency. "In addition, in X-linked adrenoleukodystrophy patients, the combination of methylation levels of SPG20, UNC45A, and COL9A3 and also the expression levels of ID4 and MYRF would be a good marker for distinguishing the discriminating childhood from adult inflammatory phenotypes." (PMID 33691689, 2021).
cancer (8 papers, 2012 to 2024). A tumor composed of atypical neoplastic, often pleomorphic cells that invade other tissues. "Unc45a has been linked to cancer progression through its overexpression and ability to confer resistance to histone deacetylase inhibitors and retinoic acid." (PMID 23144999, 2012). "A large amount of evidence has revealed that the expression of UNC45A in cancer cells is related to the proliferation and metastasis of solid tumors." (PMID 38730335, 2024). "The UNC45A mutation detected in the brain metastasis HROBML01 and its corresponding PDCs contributes to tumorigenesis and its expression in cancer cells correlates with proliferation and metastasis of solid tumors." (PMID 37228492, 2023). "CHK1 localizes in centrosome and interacts with UNC45A to regulate cancer cell proliferation." (PMID 32194790, 2020). "In the human network, we also found a significant enrichment for developmental signaling pathways, exemplified by proteins like ID3 and UNC45A, which are involved in cell differentiation and proliferation, and which interact with the cancer drivers MAX and TCF12 respectively." (PMID 26576632, 2015). "NEK7 overexpression in HeLa and MDA-MB-231 cells, which have been silenced for the UNC45A gene, restored cell proliferation, showing that NEK7 is a key downstream protein of UNC45A that mediates cell proliferation in cancer cells." (PMID 32294979, 2020). "Some of them were previously demonstrated to play a role in other cancers (UNC45A, STK11IP), and some were not yet characterized (RHPN2 and ZNFX1)." (PMID 33041669, 2020).
UNC45A also shares sentences with these, for which no sentence is quoted: colon adenocarcinoma (1 paper); diarrheal disease (1); glioma (1); heart failure (1); intestinal disorder (1); tumours (1).